GATA3 (GATA binding protein 3)
Diseases named in the same sentence as GATA3 in open-access papers (continued):
Sharing a sentence is not in itself a finding about the gene and the disease.
cancer (continued). "Given that GATA3 can bind to N-HIF-1α, we tested whether this construct without transactivation domain could block GATA3-mediated cancer cell invasiveness." (PMID 28263977, 2017).
infection (117 papers, 2005 to 2025). The state of being infected such as from the introduction of a foreign agent such as serum, vaccine, antigenic substance or organism. "TLN CD4+ T cells retained GATA‐3 protein expression at d 60 pi, indicating that the loss of GATA‐3 is restricted to the hypo‐responsive phenotype at the infection site." (PMID 40755147, 2025). "In this study, we demonstrate that Th2 cell‐intrinsic hypo‐responsiveness associates with a PD‐L2‐dependent loss of GATA‐3 expression by T cells at the infection site." (PMID 40755147, 2025). "As GATA‐3 is required to initiate and maintain the Th2 cell phenotype, its loss between d 20 and d 60 of infection is a potential mechanism by which Th2 cells are able to diverge from a classical Th2 phenotype." (PMID 40755147, 2025). "PD‐L2 downregulates GATA‐3 in T cells and induces Th2 cell‐intrinsic hypo‐responsiveness, resulting in a dysfunctional Th2 cell response and susceptibility to infection." (PMID 40755147, 2025). "The immune function and chromatin remodelling family of GATA transcription factors are associated by the inclusion of SNPs near HIVEP1 (rs10755709), which encodes a viral-infection regulation transcription factor, and GATA3 (rs71481792)." (PMID 34210368, 2021). "The inhibition of GATA3 caused the inhibition of sympathetic neuron development in the brain after DTMUV infection." (PMID 32244328, 2020). "For Gata3 expression, we have found epidemiological association with macroparasite infection, consistent with its putative role in Th2 responses." (PMID 28817724, 2017). "This is suggestive of the process, and not just the pattern, of tolerance, as the increase in body condition associated with macroparasite infection and Gata3 expression is indicative of a protective response that does not affect the parasite directly." (PMID 25004450, 2014). "All three shRNAs caused significant repression of GATA3 mRNA, but sh299 was the most efficient, with a 20-fold decrease 72 hours after infection." (PMID 19735555, 2009). "For GATA-3, these data reinforce the conclusion that while wild-type infection results in a 2–3-fold loss of GATA-3 expression, alt-transgenic infected macrophages maintain the level of this transcription factor throughout the course of in vitro infection." (PMID 15788098, 2005). "To determine the type of cellular response induced upon infection in the immunized mice and controls, we evaluated the expression of the transcription factors T-bet, GATA-3 and RORγt, respectively, associated with Th1, Th2 and Th17 cell populations in antigen-experienced (CD44+) CD4+ T cells." (PMID 35746533, 2022). "Interestingly, expression of GATA3, associated with Th2 cells, was reduced with both vaccination and infection." (PMID 34935643, 2021). "We observed an infection-associated increase in GATA-3 expression in most immature cells." (PMID 28671989, 2017). "However, Th1 markers expression was preceded (at 14 days post-infection) by expression of the master regulator transcription factor for Th2 cells, GATA3, and the associated Th2 cytokine, IL-4." (PMID 28103263, 2017). "Thus, as immature males aged, their infections reduced, consistent with the development of acquired resistance; also, mitogen-stimulated splenocyte Gata3 expression (Gata3mit-stim) was inversely associated with macroparasite infection in these animals." (PMID 25004450, 2014). "QRT-PCR analysis revealed that, relative to the Pm-infected group, the expression levels of IFN-γ, IL-4, IL-6, IL-17, TGF-β, GATA-3, T-bet, RORγt, and FoxP3 genes were significantly elevated in the Pm_OMVs-infected group at 24 hours post-infection (P < 0.01)." (PMID 41306977, 2025). "Accordingly, the overall frequencies of GATA-3+ effector cells recruited to the gut by day 6 and 14 p.i. were similar between untreated infection controls and IFN-γ treated animals." (PMID 39910093, 2025).
infection (continued). "This contrasted with C57BL/6 mice which required two weeks to build up maximal small intestinal Th2 responses and still harbored high frequencies of dividing cells in the intestinal GATA-3+ cell pool at day 14 post-infection." (PMID 39910093, 2025). "Expectedly, the majority of GATA-3+ cells proliferated in MLN of both mouse lines at day 7 post-infection." (PMID 39910093, 2025). "Here, we compared two mouse lines differing in resistance to infection with the enteric nematode Heligmosomoides polygyrus bakeri despite the similar instruction of GATA-3+ T effector cells." (PMID 39910093, 2025). "We examined the timing of this effect by infecting cells with Lv-GATA3 and measuring mRNA expression at 4, 24, and 48 h post-infection." (PMID 41422349, 2025). "The immune profile in CLN closely resembled that of MLN, characterized by a robust expansion of GATA-3+ Th2 effector cells at days 6 and 14 post-infection." (PMID 40092986, 2025). "Eight days post-infection (d.p.i), the peak of response to S.v., which is cleared around 14 d.p.i., the frequencies of inflammatory Th2 cells (expressing GATA3+) in the gLNs of H.p.- and S.v.-infected mice were similar." (PMID 39700315, 2025). "Accordingly, BALB/c mice displayed a gradual delay in the recruitment of GATA-3+ cells to the infected gut along age on day 6 post infection." (PMID 39910093, 2025). "GATA-3+ T cells isolated from MLN on day 7 post-infection comprised high proportions of α4β7+ cells in both mouse lines." (PMID 39910093, 2025). "CCR9-mediated gut homing of GATA-3+ cells is shown to correlate with high expression of aldehyde dehydrogenase (ALDH) in DCs isolated from the MLN of mice early during infection." (PMID 40092986, 2025). "To address this, we nucleofected Cas9/single-guide RNA (sgRNA) ribonucleoprotein (RNP) complexes targeting GATA3 or FOXP1 into HIV-GFP-infected primary CD4+ T cells at 1 week post infection." (PMID 38902848, 2024). "Whereas Ikaros and Gata3 were more strongly induced by M‐CSF in uninfected mice, Tbet and Eomes were preferentially induced after infection." (PMID 37635627, 2023). "There was an increase in Rora+CD4 T cells and CD45+CD3+CD4+GATA3+ cells in the lungs of mice postinfection, with the highest frequency in cells during a secondary infection." (PMID 37387671, 2023). "GATA-3 mRNA expression is observed in the spleens of dogs in the first month following experimental infection with L. infantum, with detection of Th2-type cytokine mRNA (i.e., IL-4)." (PMID 36719867, 2023). "The research on the immune response of C. gigas after infection with V. splendidus found that the expression of GATA3 and other immune-related proteins is significantly upregulated, indicating the key role of GATA3 in defending the invading pathogens." (PMID 38203295, 2023). "To assess the functional polarization of hepatic CD4- and CD4+ iNKT cells in more detail we analyzed T-bet and GATA-3 expression in the steady state and during acute and secondary infection." (PMID 36159876, 2022). "GATA-3+ cells circulating in blood of mature mice comprised significantly higher proportions of T-bet co-expressing Th2/1 hybrid cells at day 7 and 14 post infection." (PMID 35690651, 2022). "This was primarily due to the strong expansion of Th2/1 hybrid cells and was reflected in a drastic rise in IFN-γ production by GATA-3+ cells isolated from the spleen at day 28 post infection." (PMID 35690651, 2022). "In the MLN, infection induced a clear Th2 response, shown by increased expression of the Th2 master transcription factor GATA3 and the Th2 cytokines IL-5 and IL-13 in CD4+ CD44hi cells, and this response was not affected by the blockade of IL-10 signalling." (PMID 35428872, 2022). "Numbers of iNKT cell subsets remained stable during infection except for a significant expansion of GATA3-Tbet-/+ CD4+ cells at day 14 pi and day 5 pri." (PMID 36159876, 2022).
infection (continued). "In hepatic iNKT cells IL-13 production during infection was linked to GATA-3+T-bet+ CD4+ and CD4- subsets while IL-4 and IFN-γ was produced by GATA-3+T-bet+ as well as GATA-3-Tbet+/- cells." (PMID 36159876, 2022). "At four weeks post infection, the early systemic shift in favor of Th2/1 cells observed in blood of the older cohort was reflected in higher frequencies of GATA-3+ T-bet+ cells populating the siLP of mature compared to young adult mice." (PMID 35690651, 2022). "Rather, BALB/c mice treated with IFN-γ early during infection displayed a remarkable rise of GATA-3+ effector cells due to much stronger Th2/1 hybrid responses." (PMID 35690651, 2022). "Significant increases in the gene expression of two transcription factors, T-bet and GATA3, were observed in response to infection with both V. cholerae strains, as were levels of mucosal related antibodies." (PMID 34888255, 2021). "The transcription factor analysis of H→M trajectory of T cells showed that activation of GATA3 coincides with decreased cytokine secretion and a better infection outcome." (PMID 33923155, 2021). "On the other hand, the deficiency of certain T cell-related functions (complement pathway and binding of GATA3) will likely lead to severe infection." (PMID 33923155, 2021). "At all three time points after infection both T-bet and GATA-3 gene expression were significantly increased in zebrafish infected with either of the V. cholerae strains as compared to uninfected control fish." (PMID 34888255, 2021). "Though Foxp3+ Treg expansion has been observed in the mLN of S. ratti-infected mice, we did not observe increased frequencies of polyclonal Foxp3+ and Foxp3+GATA3+ CD4+ T cells in the lungs of mice 14 days post S. ratti-infection relative to naïve mice." (PMID 34237106, 2021). "A previous report was able to evidence an increase in the frequency of GATA3 CD4 T cells following infection with Trichuris suis, but, in agreement with our result, was not demonstrated after PRRSV infection." (PMID 34956200, 2021). "In this study, we evaluated the expressions of different TFs (T-bet, GATA3, FOXP3, and EOMES) through RT-qPCR and the associated cytokine profiles during infection with PRRSV-1 strains of different virulence in target organs." (PMID 34956200, 2021). "Consistent with the systemic alarmin function of HA fragments as a DAMP, we observed a greatly decreased induction of CD4+ cells expressing Tbet, GATA3, RORγt, INFγ, and1 IL-17 in Cemip−/− mice following infection." (PMID 31914398, 2020). "The expression of GATA-3 and T-bet was significantly higher than the time-matched plasmid controls at all timepoints pre (day 2 and 7) and post-infection (day 19, 22 and 28) at the injection site." (PMID 32326041, 2020). "In contrast, a marked increase in counts of tuft cells and GATA3+ cells was observed as a consequence of the secondary infection." (PMID 33276813, 2020). "Following overexpression by GATA-3, the expression of IL-4/13A in the spleen was significantly higher (p < 0.05) on day 19 (day 4 post-infection) relative to the controls." (PMID 32326041, 2020). "Intriguingly the mRNA levels of RELM-β in exfoliated cells reflected the local GATA-3 and IL-13 expression in mLN during infection." (PMID 30915083, 2019). "Subsequently, we measured the RNA and protein expression of GATA3 upon silencing KIAA1429 by transfection with siRNAs or infection with lentivirus-packaged shRNA." (PMID 31856849, 2019). "These qRT-PCR data revealed that Curdlan treatment results in a dampened expression of GATA3 at day 10, which is significantly reduced at day 28 after infection compared to control animals." (PMID 29535708, 2018). "Upon infection, however, we detected GATA-3+Treg as the dominant IL-10+ Treg source in the small intestine and mLN of SPF as well as GF mice." (PMID 30349532, 2018). "Upon infection, the increase in GATA-3+Treg reached significance in the small intestine of SPF mice." (PMID 30349532, 2018).
infection (continued). "Both CD4+ T-bet+ cells and CD4+ GATA-3+ cells significantly increased following intraportal inoculation of S. mansoni-eggs as well as after S. mansoni-cercariae infection." (PMID 29373600, 2018). "Adult worms are rapidly cleared after challenge infection due to a highly polarized Th2 immune response critically dependent on IL-4-producing CD4+GATA3+ T cells, alternatively activated macrophages (AAMØ), B cells, and parasite-specific IgG1." (PMID 28968468, 2017). "Among the genes associated with responses to virus, TLR3, IRF1, GATA3, SAMHD1 and RSAD2 were all significantly up-regulated on both day 1 and day 3 post infection." (PMID 28486945, 2017). "In the present study, to determine the roles for T-bet and Gata3 overexpression in TMEV infection, we inoculated wild-type mice, T-bet-tg mice, and Gata3-tg mice on the resistant C57BL/6 mouse background with TMEV." (PMID 28874814, 2017). "Negatively selected CD4+ T cells from WT and ΔdblGATA brains after 1 and 2 wks of infection were compared at the transcript level for Il4 and Gata3 (a transcription factor involved in polarizing T cells towards Th2 phenotype) expression." (PMID 27332553, 2016). "In order to determine the mRNA levels of the major T cell transcription factors (Foxp3, Tbet, GATA3 and RORγC) after reconstitution of Rag1-/- mice, RT-PCR analyses of total lung RNA were performed after 2 and 6 weeks of infection." (PMID 26512987, 2015). "Later on in infection, at week 10, the increase in the mRNA levels of Tbet, GATA3 and RORγC paralleled the reduction in expression levels of the Treg-associated molecules Foxp3, PD-L1, CCR5, CCR6 and Granzyme B." (PMID 26512987, 2015). "Although the proportion of GATA-3+ Treg cells increases with infection in both strains, the proportion of GATA-3+ Treg cells and expression of GATA-3 within the MLNC Treg-cell population remains significantly lower in IL-6−/− mice." (PMID 24185641, 2014). "Time series data for individual animals suggested that macroparasite infections gave rise to increased expression of Gata3, which gave rise to improved body condition and enhanced survival as hosts aged." (PMID 25004450, 2014). "CCR5-/- mice were extremely susceptible to infection, presenting higher parasite load and lower tissue expression of IL-12p40, IFN-γ, TNF, IL-6, iNOS, Foxp3, T-bet, GATA-3 and PPARα." (PMID 25119429, 2014). "Some corroborative patterns were also seen for another chronic infectious disease, TB, with animals being in better condition if showing overt signs of infection and especially if also expressing high levels of Gata3." (PMID 25004450, 2014). "The biomarker, Gata3, is triggered by infection, precedes significant changes in body condition, and impacts on fecundity and survival." (PMID 25004450, 2014). "Infection with Schistosoma mansoni cercariae induced bona fide Th2 cells expressing GATA-3 as well as a substantial cell population co-expressing GATA-3 and T-bet at the single-cell level as cell-autonomous hybrid cells." (PMID 23976880, 2013). "On d 9, at the peak of the effector T cell response, T-bet expression by hybrid Th1/2 cells was Th1-like while GATA-3 expression was intermediate (unpublished data), as seen after local infection, a behavior mirroring the plasticity of classic Th2 cells." (PMID 23976880, 2013). "Contrary to the pattern of Th1-type response gene expression, 5 of the 14 Th2 type response genes (IL5, CCL11, CCR3, IL1RA and GATA3) were significantly downregulated at 2, 4, 8 and 12 weeks post-infection." (PMID 23448601, 2013). "This was accompanied by abundant CD4+ and CD8+ T cells exhibiting an activated phenotype and induction of interleukin 13 (IL-13)- and GATA3-expressing Th2-type CD4+ T cells that remained present in the airways even 14 days after infection." (PMID 23926350, 2013).